IL6 (interleukin 6)
Diseases named in the same sentence as IL6 in open-access papers (continued):
Sharing a sentence is not in itself a finding about the gene and the disease.
myasthenia gravis (6 papers, 2009 to 2025). Myasthenia gravis (MG) is a rare, clinically heterogeneous, autoimmune disorder of the neuromuscular junction characterized by fatigable weakness of voluntary muscles. "Studies by Revital Aricha and Akiyuki Uzawa indicated that blocking IL-6 could suppress experimental autoimmune myasthenia gravis (EAMG) and that high serum IL-6 levels were associated with disease activity in MG, respectively." (PMID 40689326, 2025). "On the other hand, elevated levels of pro-inflammatory effector T cell cytokines such as IFN-γ, IL-17 as well as IL-6 are noted in patients with autoimmune myasthenia gravis and MS." (PMID 32102262, 2020). "Further studies affirm this observation, indicating a significant role of inflammatory markers such as IL-6 and TNF-α in the decline of muscle strength and the onset of myasthenia gravis." (PMID 37789429, 2023).
obstructive jaundice (6 papers, 1994 to 2024). A finding indicating increased bilirubin levels in the blood and urine, due to intrahepatic or extrahepatic obstruction of the biliary system. "Clinical studies have shown that patients with obstructive jaundice are predisposed to systemic inflammatory reactions characterized by high levels of pro-inflammatory cytokines [e.g., IL6 and TNF (tumor necrosis factor, TNF-α)]." (PMID 38319509, 2024). "Therefore, based on our research and previous reports, we speculate that an increase in IL-6, similar to IL-6 deficiency, increases the susceptibility of animals with obstructive jaundice to endotoxins and leads to excessive lung inflammation and damage." (PMID 39744639, 2024). "It reduced the expression of tumor necrosis factor-alpha (TNF-α), nuclear factor kappa B (NF-κB), transforming growth factor-beta (TGF-β), interleukin-6 (IL-6) mRNA in mouse serum, and restored liver cells in obstructive jaundice mice." (PMID 38998501, 2024). "We have investigatedthe relationship of obstructive jaundice to the neutrophil oxidase response and the “priming” of theresponse by the cytokines TNFα, interleukin-1 (IL-1), IL-6, and IL-8." (PMID 8204547, 1994). "Notably, the lack of IL-6 enhanced the susceptibility of mice with obstructive jaundice to endotoxins and led to more extensive lung inflammation, which seems to suggest that IL-6 may have a protective effect." (PMID 39744639, 2024). "To further evaluate the excessive pulmonary inflammation induced by LPS in rats with obstructive jaundice, we observed changes in the expression of inflammatory cytokines TNF-α and IL-6 in lung tissue." (PMID 39744639, 2024).
opisthorchiasis (6 papers, 2012 to 2019). Infection with flukes of the genus Opisthorchis. "Elevated plasma concentrations of IL-6 are associated with a significant dose-dependent increase in the risk of opisthorchiasis-associated advanced periductal fibrosis and CCA." (PMID 31121000, 2019). "Elevated plasma interleukin-6 (IL-6) is associated with marked increase in risk of periductal fibrosis during opisthorchiasis and compounds pathogenesis by promoting a fibrogenic inflammatory milieu." (PMID 28750101, 2017). "It is only in the presence of advanced pathology from chronic opisthorchiasis that plasma concentrations of IL-6 are significantly elevated." (PMID 22629477, 2012). "Biomedical studies show that opisthorchiasis-induced inflammation can lead to the development of O. viverrini-induced advanced periductal fibrosis (APF) and CCA, which are driven by common cellular mechanisms, marked by elevated level of plasma interleukin-6." (PMID 27926938, 2016).
paracoccidioidomycosis (6 papers, 2017 to 2024). A systemic fungal infection caused by Paracoccidioides brasiliensis that is most often seen in immunocompromised patients. "Paracoccidioidomycosis also showed that IL-6, IL-23, or IL-17RA receptor deficiency impaired granuloma formation and conferred susceptibility during infection." (PMID 35844540, 2022).
peripheral arterial occlusive disease (6 papers, 2015 to 2023). "Serum concentrations of VEGF-C and IL-6 were significantly increased in patients showing moderate or severe peripheral artery stenosis." (PMID 37446302, 2023). "IL-6 levels are correlated with AM levels in major abdominal surgery and peripheral arterial occlusive disease." (PMID 34179545, 2021). "Δ phosphate, Δ calcium and Δ albumin were calculated as valueFollow up−valueBaseline Abbreviations: Body mass index (BMI); Vitamin D receptor activators (VDRA); coronary heart disease (CHD); peripheral arterial occlusive disease (PAOD); Interleukin-6 (IL-6)." (PMID 29042624, 2017).
peripheral vascular disease (6 papers, 2007 to 2023). Any disorder affecting blood flow through the veins or arteries outside of the heart. "Studies also demonstrated that AD-MSCs promoted angiogenesis in ischemic heart and cerebral diseases and peripheral vascular disease, via secreting angiogenic factors including VEGF, bFGF, IL-6, and transforming growth factor α (TGF-α)." (PMID 34512766, 2021). "The serum levels of TNF-α, IL-6, and C-reactive protein (CRP) were also higher in subjects with arteriosclerotic peripheral vascular disease compared to healthy controls." (PMID 24766841, 2014).
placental insufficiency (6 papers, 2007 to 2022). Failure of the placenta to deliver an adequate supply of nutrients and oxygen to the fetus. "In a study on maternal peripheral blood lymphocytes, IL-6 levels increased in FGR pregnancies with placental insufficiency, and IL-6 acts as a potential marker of the inflammatory process." (PMID 35563719, 2022). "In summary, we believe that this study showed the effect of maternal obesity on placental vascularization and suggested that IL-6-mediated EC senescence could contribute to the observed placental insufficiency thereby adding clinically relevant insight." (PMID 31979004, 2020). "Furthermore, elevated maternalTNF-alpha, IL-6, IL-8, and macrophage colony-stimulating factor concentrations have been observed in IUGR due to placental insufficiency." (PMID 18274642, 2007). "Two of the ratios, IL-6/IL-13 (P < 0.006) and IL-8/IL-13 (P < 0.001), were significantly higher in IUGR without placental insufficiency compared to normal pregnancy." (PMID 22110537, 2012).
premature ovarian failure (6 papers, 2021 to 2024). "In addition, it was found that IL-17A/IL-6 axis expression was up-regulated in a cyclophosphamide (CTX)-induced model of premature ovarian failure in rats, significantly regulating the activities of REK1/2 and MEK1/2." (PMID 39568012, 2024). "In addition, circulating IL-6 levels were significantly higher in patients with premature ovarian failure than in normal controls." (PMID 39639885, 2024).
Premature rupture of membranes (6 papers, 2020 to 2025). Premature rupture of membranes (PROM) is a condition which occurs in pregnancy when the amniotic sac ruptures more than an hour before the onset of labor. "A meta-analysis of 694 neonates showed higher sensitivity and specificity of IL-6 (pooled sensitivity 85% and specificity 88%) in infants with premature rupture of membranes." (PMID 36830264, 2023). "Previously it has been shown that, in the presence of premature rupture of membranes, maternal serum IL-6 predicts preterm delivery at 72 h before delivery." (PMID 32652973, 2020).
Pulmonary hemorrhage (6 papers, 2015 to 2025). Pulmonary hemorrhage is a bleeding within the lungs. "Elevated levels of cytokines, especially IL-6, increase alveolar-capillary permeability and pulmonary hemorrhage." (PMID 39839732, 2024). "Patients with severe pulmonary haemorrhage had significantly higher levels of IL-5, IL-6, IL-8, and IL-10." (PMID 32264832, 2020). "Co-injection of recombinant Rv0888NS/MS with an MPO inhibitor remarkably decreased recombinant Rv0888NS/MS-induced pulmonary hemorrhage, infiltration of inflammatory cells, and release of inflammatory cytokines (IL-6, TNF-α and IL-1β)." (PMID 29670633, 2018).
respiratory syncytial virus infection (6 papers, 2010 to 2025). "Respiratory syncytial virus infection generates intense neutrophilic infiltration, release of IL-6, IL-8, TNF-α, and proteolytic enzymes, contributing to epithelial fragility." (PMID 41459355, 2025). "Using murine alveolar epithelial cells or macrophage cells, the involvement of the MAPK signal pathway has been demonstrated in the IL-6 group of cytokines, oncostatin M- or respiratory syncytial virus infection-augmented IL-33 expression and production." (PMID 29587772, 2018). "Serum IL-6 concentrations in patients with adenoviral respiratory infection were higher than those in patients with other viral respiratory tract infections (like influenza virus and respiratory syncytial virus infection)." (PMID 40506878, 2025).
retinal vein occlusion (6 papers, 2019 to 2023). An occlusion of the retinal vein. "Two of the major causes of VEGF induction include IL-6 and hypoxia, both of which are present in ocular pathologies such as retinal vein occlusions." (PMID 36902105, 2023).
sporotrichosis (6 papers, 2018 to 2024). The commonest and least serious of the deep mycoses, characterized by nodular lesions of the cutaneous and subcutaneous tissues. "Expression levels of TNF and IL-6 in the lesional skin of sporotrichosis patients were markedly higher as compared to healthy control skin." (PMID 32265923, 2020). "The results of our analyses of TNF and IL-6 expression in sporotrichosis patients suggest that this is so." (PMID 32265923, 2020). "Serum levels of TNF and IL-6 were highest in patients of disseminated type sporotrichosis, followed by patients with lymphocutaneous sporotrichosis, and lowest in fixed cutaneous sporotrichosis patients." (PMID 32265923, 2020). "Finally, TNF and IL-6, in the context of sporotrichosis, may also be produced by cells other than MCs, for example T cells and macrophages." (PMID 32265923, 2020). "In patients with sporotrichosis, TNF and IL-6 were increased in skin lesions, and markedly elevated levels in the serum were linked to disease activity." (PMID 32265923, 2020). "Patients with sporotrichosis showed markedly higher serum levels of TNF and IL-6 than healthy controls (HC; TNF-α: 53 ± 24 vs. 6 ± 10 pg/ml, P < 0.001; IL-6: 80 ± 42 vs. 25 ± 10 pg/ml, P < 0.001)." (PMID 32265923, 2020). "Taken together, our present study provides evidence that MCs exacerbate mouse and human skin S. schenckii infection and sporotrichosis by releasing TNF and IL-6." (PMID 32265923, 2020). "Taken together, our results suggest, but do not prove, that MC-derived TNF and IL-6 contribute to the pathology of sporotrichosis." (PMID 32265923, 2020). "Immunization with rSsEno plus PGA induced a predominantly T-helper 1 cytokine pattern after in vitro stimulation of splenic cells with rSsEno: elevated levels of IFN-γ and IL-2, as well as of other cytokines involved in host defense against sporotrichosis, such as TNF-alpha, IL-6, and IL-4." (PMID 31748544, 2019). "The results showed that the protein expressions of IL-6, JAK3, STAT3, and SOCS3, as well as phosphorylated JAK3 and STAT3, were significantly upregulated, suggesting that the JAK/STAT signaling pathway was activated during the occurrence and development of sporotrichosis." (PMID 38172590, 2024). "Also, two case reports describe the development of sporotrichosis in patients treated with TNF antagonists, whereas there are no reported cases of treatment for sporotrichosis with a TNF antagonist or anti-IL-6." (PMID 32265923, 2020). "Another limitation of this study was the absence of a control group of healthy cats, so that it cannot be confirmed whether IL-6 levels are altered in cats with sporotrichosis, co-infected with retrovirus infections or not, in comparison to healthy cats." (PMID 30500849, 2018).
staphylococcal infection (6 papers, 2010 to 2022). An infection caused by Staphylococcus. "Autoantibodies against IL-6 have yet been described in only few patients, but seem to predispose to pneumococcal and staphylococcal infections." (PMID 32419033, 2020). "This notion is supported by a report describing severe staphylococcal infection in a child with anti-IL6-antibodies, providing further evidence that IL6 is critical in response to human infection with staphylococci." (PMID 30671054, 2018). "In addition, the course of clinical events in the patient was suggestive of an occurrence of anti-IL-6 autoantibodies that preceded staphylococcal infection." (PMID 21079687, 2010). "Inborn errors of the IL-6 pathway and acquired autoantibodies against IL-6 have been detected in patients with HIES and staphylococcal infections, respectively." (PMID 36094518, 2022). "This is well in line with the rarity of staphylococcal infections in APECED patients, and argues strongly against our hypothesis that anti‐IL‐6 autoantibodies are involved in the pathogenesis of CMC in APECED patients." (PMID 27957331, 2016). "Since IL-6 is pivotal for CRP induction, these results indicated that anti-IL-6 autoantibodies contributed to the lack of CRP response in this patient during staphylococcal infections." (PMID 21079687, 2010).
synovial sarcoma (6 papers, 2014 to 2025). "Here, we show that TRYP and TRYP-Ox significantly inhibited IL-1β–induced IL-6 secretion by SW982 synovial sarcoma cells and THP-1 monocytic cells, with TRYP-Ox being far more effective than TRYP." (PMID 32792961, 2020). "Indeed, our data show that siRNA knockdown of VAMP3 impairs IL-6 secretion by monocyte-derived dendritic cells as previously observed for RAW264.7 murine macrophages and SW982 human synovial sarcoma cells." (PMID 28524818, 2017).
tenosynovitis (6 papers, 2015 to 2025). Inflammation of the synovial lining of a tendon sheath. "This study employed a two-sample Mendelian randomization (MR) approach to evaluate the potential causal association between circulating IL-6 levels and the risk of tenosynovitis." (PMID 41088586, 2025). "Joint pain in SLE patients results from tenosynovitis, and the cytokine IL-6 has been associated with “the worst joint pain”18,34." (PMID 39525758, 2024). "This study, based on MR, explores the potential association between IL-6 levels and the risk of tenosynovitis from a genetic perspective, showing a non-significant negative trend." (PMID 41088586, 2025). "Previous studies have suggested that interleukin-6 (IL-6) may play a critical role in tendon injury and repair; however, definitive evidence regarding a causal relationship between IL-6 levels and the risk of tenosynovitis remains lacking." (PMID 41088586, 2025). "This is probably due to increased levels of IL-6 and IFN-γ cytokines corresponding with lymphocytic infiltration in gastrocnemius tendon sheath, indicating the role of these cytokines in the development of tenosynovitis." (PMID 35455235, 2022).
tonic-clonic seizures (6 papers, 2013 to 2023). "Previous reports have shown an increase in IL-6 concentration in the cerebrospinal fluid of patients with tonic-clonic seizures, and there are complex interactions between the immune system and the nervous system." (PMID 37946105, 2023). "In line with that, human CAE is known to be associated with detectable levels of IL-6 and IL-8 in the cerebrospinal fluid and treatment with valproic acid reduces IL-6 serum levels in children with tonic-clonic generalized seizures." (PMID 34177766, 2021).
trachoma (6 papers, 2008 to 2020). "New risk factors for chronic scarring trachoma included IL-6 and IL-15 (r = 0.259 and 0.292, respectively, P<0.005 for both) with increased levels for concurrent C. trachomatis infections (r = 0.206, P<0.05, and r = 0.304, P<0.005, respectively)." (PMID 18628987, 2008). "Indeed, we have identified an IL-6-driven pro-fibrotic/pro-inflammatory feedback loop that may contribute to chronic scarring in trachoma, possibly underlying the recently uncovered link between clinical inflammation and progressive scarring." (PMID 27321784, 2016). "We further demonstrate that scarring trachoma fibroblasts can promote Akt phosphorylation in macrophages in an IL-6 –dependent manner." (PMID 27321784, 2016). "In trachoma, we demonstrated elevated levels of IL-6 during both acute and chronic grades of infection, with detectable chlamydial cases exhibiting more pronounced concentrations." (PMID 22894815, 2012). "This has been demonstrated by persistent elevation of pro-inflammatory cytokines like IL-6 among infertile women and in tear fluid from post-scarring trachoma populations." (PMID 22894815, 2012). "One previous study evaluated IL-6 gene expression in trachoma but the findings were inconclusive due to detectable mRNA levels in only two patients." (PMID 18628987, 2008). "Using this model, we identified an IL6-mediated pro-fibrotic and pro-inflammatory feedback loop that could participate in trachoma progression, further demonstrating the suitability of the model to study the pathophysiology of conjunctival scarring." (PMID 33141875, 2020). "They went on to suggest that increased IL-6 secretion in trachoma may sustain macrophage activation and survival, with the knock-on effect that this could enhance the contractile activity of the fibroblasts and lead to more severe scarring." (PMID 29967566, 2018). "Kechagia and colleagues showed that trachoma fibroblasts could promote Akt phosphorylation in macrophages in an IL-6-dependent manner." (PMID 29967566, 2018). "In addition, we identify IL-6 as a signature gene for scarring trachoma, and demonstrate that its main role is in modulating the local immune response, potentially contributing to the chronic activation of the fibroblasts." (PMID 27321784, 2016). "We found elevated IL-6 production for all grades of trachoma." (PMID 18628987, 2008). "However, IL-6 protein levels were significantly elevated among cases with TT compared to controls (P<0.01) as in the other trachoma grades." (PMID 18628987, 2008). "Thus, increased IL-6 secretion in trachoma may sustain local macrophage survival and activation, which in turn could further the contraction activity of the fibroblasts." (PMID 27321784, 2016).
Tremor (6 papers, 2015 to 2024). An unintentional, oscillating to-and-fro muscle movement about a joint axis. "When early stage and late stage CSF cytokines were compared, IL-10 and IL-6 were up regulated in late stage patients and were associated with a reduction in tremors and cranioneuropathy." (PMID 26090964, 2015). "Moreover, similarly to the presented results, they showed that the non-tremor form of PD had significantly lower serum IL-6 concentrations." (PMID 38392998, 2024).